MUC2 (mucin 2, oligomeric mucus/gel-forming)
Description:
Coats the epithelia of the intestines and other mucus membrane-containing organs to provide a protective, lubricating barrier against particles and infectious agents at mucosal surfaces. Major constituent of the colon mucus, which is mainly formed by large polymeric networks of MUC2 secreted by goblet cells that cover the exposed surfaces of intestine. MUC2 networks form hydrogels that guard the underlying epithelium from pathogens and other hazardous matter entering from the outside world, while permitting nutrient absorption and gas exchange. Acts as a divalent copper chaperone that protects intestinal cells from copper toxicity and facilitates nutritional copper unptake into cells. Binds both Cu(2+) and its reduced form, Cu(1+), at two juxtaposed binding sites: Cu(2+), once reduced to Cu(1+) by vitamin C (ascorbate) or other dietary antioxidants, transits to the other binding site. MUC2-bound Cu(1+) is protected from oxidation in aerobic environments, and can be released for nutritional delivery to cells. Mucin gels store antimicrobial molecules that participate in innate immunity. Mucin glycoproteins also house and feed the microbiome, lubricate tissue surfaces, and may facilitate the removal of contaminants and waste products from the body. Goblet cells synthesize two forms of MUC2 mucin that differ in branched chain O-glycosylation and the site of production in the colon: a (1) 'thick' mucus that wraps the microbiota to form fecal pellets is produced in the proximal, ascending colon (By similarity). 'Thick' mucus transits along the descending colon and is lubricated by a (2) 'thin' MUC2 mucus produced in the distal colon which adheres to the 'thick' mucus (By similarity).
Synonyms: MUC-2; SMUC; MLP
Gene: Protein-coding gene on chromosome 11 (1,074,875 to 1,110,511, forward strand). Ensembl gene ENSG00000198788.
Subcellular location: Secreted
Genetic constraint (gnomAD): Loss-of-function variants: 105 observed, 148.59 expected, observed/expected ratio (o/e) 0.71, 90% interval 0.6 to 0.83. The upper end of that interval is the gene's LOEUF score, 0.83, which puts it in group 3 of 6, group 1 being the genes least tolerant of losing a copy. Missense variants: 1,846 observed, 1,849.3 expected, observed/expected ratio (o/e) 1, 90% interval 0.96 to 1.04. Synonymous variants: 880 observed, 771.86 expected, observed/expected ratio (o/e) 1.14, 90% interval 1.08 to 1.21.
Homologues: Orthologues: pig MUC2 (79% identical), dog MUC2 (77% identical). Paralogues in human: MUC5AC (48% identical), MUC5B (48% identical), MUC6 (35% identical), MUC19 (32% identical), VWF (29% identical), OTOG (27% identical), OTOGL (26% identical), TECTA (23% identical), FCGBP (22% identical), ZAN (16% identical), KCP (16% identical), BMPER (13% identical), and 7 more.
Diseases named in the same sentence as MUC2 in open-access papers:
MUC2 is named in the same sentence as 243 diseases in open-access papers, as found by Europe PMC text mining. Sharing a sentence is not in itself a finding about the gene and the disease. The quoted sentences say what the papers report.
colitis (357 papers, 2008 to 2026). Inflammation of the colon. "In a study, CLA production enhanced by Bifidobacterium longum CCFM681 ameliorated DSS-associated colitis by increasing MUC2, claudin-3, α-catenin 1, and ZO-1 (goblet cells involved in the protection of the intestinal mechanical barrier)." (PMID 40806004, 2025). "Degradation of Muc2 compromises mucosal defense, making the epithelium more susceptible to bacterial invasion and exacerbating colitis." (PMID 40836347, 2025). "paracasei L9 on the mucus barrier in DSS-induced colitis mice, Alcian Blue (AB) staining and gene expression quantification of mucin-associated markers (Muc1, Muc2, and Tff3) were performed." (PMID 41515240, 2025). "The O glycans that make up MUC2 studied in colitis mouse models had three primary deficiencies: terminal sialylation, fucosylation, and sulfation." (PMID 40141145, 2025). "Mice with defective MUC2 glycosylation develop spontaneous colitis, providing a model for studying colitis-associated cancer." (PMID 40141145, 2025). "A study observed that mice deficient in Core 1 glycosyltransferase exhibited MUC2 mucins with shortened O-glycans and accelerated degradation, subsequently developing severe colitis." (PMID 40292216, 2025). "Branching supports folding/trafficking; epithelial stress in colitis associates with misfolded MUC2 and barrier failure." (PMID 41301470, 2025). "Reduced expression of MUC2 is linked to associated with an increased risk of intestinal inflammation, including colitis." (PMID 40431496, 2025). "A report shows that Muc2-deficient mice spontaneously develop colitis, underlining the importance of goblet cells in barrier function." (PMID 40723826, 2025). "Early research has found that MUC2 deficiency leads to colonic inflammation in mice, which spontaneously develops colitis and later on colorectal cancer." (PMID 39263224, 2024). "Deficiency of C1galt1, critical for core 1 O-glycosylation of mucin, results in the failure of normal mucus layer formation and spontaneous development of colitis, similar to MUC2-deficient mice." (PMID 39589551, 2024). "Germline genetic knockout of the Muc2 gene in mice has been described previously as causing colitis that arises from impaired barrier function." (PMID 38199279, 2024). "Researches have demonstrated that MUC2-deficient mice were more susceptible to colitis, and the level of MUC2 expression was significantly negatively correlated with the expression of inflammatory cytokines." (PMID 39533418, 2024). "Mucin production is critical as reports suggested an increased risk of colitis and inflammation-induced colorectal cancer in MUC2 deficient mice." (PMID 39064745, 2024). "In contrast, the Mediterranean diet is low in saturated fat, although higher in unsaturated fats, and a fat blend based on this diet was shown to protect against colitis development in mucin-2 (MUC2)-deficient mice." (PMID 39683595, 2024). "Mucin proteins, such as Muc2, are produced by specialized IECs known as goblet cells to maintain the natural barrier and loss of Muc2 promotes spontaneous colitis, underlying its important role in maintaining the mucosal barrier." (PMID 38397081, 2024). "Deficiency or inadequacy of MUC2 in tissues increases the risk of diseases such as colitis and colon cancer in humans." (PMID 38066981, 2023). "Muc2-deficient mice develop spontaneous colitis with marked induction of the goblet cell mediator RELMβ." (PMID 36691020, 2023). "Goblet cell depletion and mucus production reduction seem to be important keys to the pathophysiology of IBD since animals deficient for the Muc-2 gene develop spontaneous colitis." (PMID 37443707, 2023). "MUC2-deficient mice spontaneously develop colitis, highlighting the crucial role of MUC2 in protecting against colitis." (PMID 37686390, 2023). "Several studies suggested colonic inflammation is associated with mucus layer disruption, goblet cell depletion, and reduced Muc2 synthesis." (PMID 36986258, 2023).
colitis (continued). "For example, Mucin 2 deficient (Muc2-/-) mice develop colitis at 6 months of age, with increases in Firmicutes/Bacteroidetes and some Proteobacteria (Desulfovibrio and Escherichia)." (PMID 37083032, 2023). "The resistin-like molecule beta (RETNLβ) drives spontaneous colitis in Muc2-deficient mice by promoting commensal microbial dysbiosis." (PMID 36613400, 2023). "Mice lacking Muc2, Agr2 or having mutations in Muc2 that interfere with initial mucin folding and assembly develop spontaneous colitis or display rectal prolapse." (PMID 36245281, 2023). "It has been demonstrated that MUC2-deficiency can lead to the development of spontaneous colitis with histologic damage, thinner mucus layer and increased permeability, which are susceptible to the invasion of epithelial cells by pathogens." (PMID 37430929, 2022). "Mice with MUC2 depletion developed spontaneous colitis with weight loss, changes in stool consistency, and increased inflammatory cytokine expression." (PMID 35682612, 2022). "Mice deficient in Muc2 production are more susceptible to intestinal infections and spontaneously develop colitis, suggesting mucus production protects against enteric pathogens." (PMID 35336095, 2022). "Muc2 deficiency results in impaired epithelial barrier function, imbalance in gut microbiota, spontaneous colitis, and tumor." (PMID 36425784, 2022). "Altogether, these results suggest that A. muciniphila is a potential regulator of CNS physiology in Muc2-associated colitis." (PMID 36175462, 2022). "MUC2 is secretory mucin that exists in high levels in the colon under normal conditions, and is essential for maintaining intestinal homeostasis, exemplified by MUC2-deficient mice developing colitis." (PMID 35334805, 2022). "These pathological alterations were observed in the Winnie murine model of spontaneous colitis, characterized by a missense mutation in the Muc2 gene." (PMID 35203499, 2022). "Muc2-deficient mice spontaneously contribute to the development of colitis and colorectal cancer, and at the same time, the microbial composition is different from that in wild-type mice." (PMID 36139747, 2022). "Together, these results suggest that Pectin and Tributyrin diets alleviate colitis-associated goblet cell depletion by increased secretion of Muc2." (PMID 35008767, 2021). "It is reported that Erysipelotrichaceae, Turicibacter and others are related to the elevation of TNF levels, IL levels in the Muc2 deficient mice with colitis." (PMID 34326769, 2021). "Winnie mice, carrying a Muc2 gene mutation resulting in intestinal goblet cell ER stress, develop spontaneous colitis with a depleted mucus barrier and increased bacterial translocation." (PMID 33645438, 2021). "Winnie spontaneous colitis originates from Muc2 misfolding associated ER stress and UPR activation, which further leads to impaired barrier integrity with increased bacteria translocation." (PMID 33645438, 2021). "This is supported by a previous investigation that revealed that MUC-2-deficient mice are vulnerable to colitis and death caused by CR infection." (PMID 35008767, 2021). "Decreased Muc2 production associates with UC in humans, and Muc2 –/– causes spontaneous colitis in mice, suggesting its critical role in intestinal health." (PMID 33644071, 2021). "In patients with UC and experimental colitis models, characterized by a thin mucin layer in association with goblet cell depletion, high expression of Muc1 and Muc4, and low expression of Muc2 and Tff3 have been reported." (PMID 33959000, 2021). "MUC2 and MUC3 are the two important mucins that are present in the intestines, and their expression is reduced during colitis; mice deficient in Muc2 develop spontaneous colitis." (PMID 34572293, 2021). "Previous studies have shown that the aberrant mucus barrier structure caused by Muc2 deficiency led to a more severe colonic inflammation in a mouse colitis model." (PMID 34658866, 2021).
colitis (continued). "For example, grape seed extract supplementation was associated with enhanced mRNA expression of MUC2 in IL10-deficient mice model of colitis." (PMID 33806347, 2021). "In this study, we used Mucin-2 (Muc2) knockout mice predisposed to colitis to study intestinal barrier upon chronic inflammation." (PMID 33273633, 2020). "In mice, missense mutations in the MUC2 gene (e.g., Winnie and Eeyore mouse models) result in spontaneous colitis associated with innate and Th17 immune responses, including ER stress which is accentuated by the prolonged HFD feeding in Winnie mice." (PMID 33603741, 2020). "Muc2−/− mice or those with missense mutations impairing the release of MUC2 are born with an underlying predisposition to intestinal inflammation that shows the rapid progression of colitis." (PMID 33024049, 2020). "The importance of Muc2 for maintenance of mucosal integrity is emphasized in Muc2-deficient mice, which developed spontaneous colitis and were susceptible to experimental colitis induced by dextran sodium sulfate (DSS)." (PMID 33299531, 2020). "DSS-induced colitis was also found to be associated with the decreased expression of Muc2, Claudin-1, and ZO-1." (PMID 33363184, 2020). "Mice genetically deficient in Muc2 (Muc2−/−) developed spontaneous colitis, an effect that was diminished in mice double knock out for Muc2 and RELMβ (Muc2−/−/RELMβ−/−)." (PMID 32508838, 2020). "The impaired expression of MUC2 O‐glycans and deposition of Tn/sTn antigen have recently been reported to cause colonic mucus barrier breach and contribute to colitis and associated cancer." (PMID 33040455, 2020). "In fact, MUC2-deficient (Muc2−/−) mice develop spontaneous colonic inflammation characterized by weight loss, changes in stool consistency, and increased expression of pro-inflammatory cytokines." (PMID 33013869, 2020). "Induction of colitis caused a decrease in intestinal Muc2 and TFF3 mRNA levels and an increase in STAT3 mRNA expression as compared to the control group (p < 0.01, p < 0.05, and p < 0.01, respectively)." (PMID 33299531, 2020). "Our observation of the expansion of CD103 + CD11b + cDC subset has also been associated with Muc2 deficiency in mice and spreading of spontaneous colitis." (PMID 31718550, 2019). "Muc2 deficient mice develop spontaneous colitis and are more susceptible to dextran sulphate sodium (DSS) mediated model of colitis." (PMID 30764829, 2019). "In MUC2-deficient mice, colon inflammation will occur and contribute to the development of colitis induction." (PMID 31198858, 2019). "It has been shown in the literature that mice with C1GalT1 and C3GnT knockout have increased susceptibility to colitis, MUC2 level also was decreased, the total glycan chains were shorter, and the microflora was changed." (PMID 31731602, 2019). "Decreased Muc2 has been correlated with inflammation and MUC2 deficiency leads to spontaneous colitis." (PMID 31165072, 2019). "These cells showed a protective role in gut inflammation since MUC2-null mice developed spontaneous colitis, and patients with UC showed polymorphism in MUC2 in the Dutch population." (PMID 31024529, 2019). "Genetic deficiency of the Muc2 gene results in 90% reduction in mucus and increased exposure of the intestinal epithelial cells to the luminal contents, causing spontaneous colitis and CRC." (PMID 30231491, 2018). "In the present study, DSS-induced colitis was also associated with a reduction in the expression of mucins, MUC-2 and MUC-3, and tight junction proteins, OCLN and ZO-1, which participate in maintaining epithelial integrity." (PMID 29867475, 2018). "At 3 months of age, Muc2 deficient mice spontaneously present with colitis that progresses over the following months and mimics several aspects of the human disease." (PMID 30319652, 2018). "Gut dysbiosis is associated with colitis-associated colorectal carcinogenesis, and the genetic deficiency of the Muc2 gene causes spontaneous development of colitis and colorectal cancer." (PMID 30231491, 2018).
colitis (continued). "For example, 5 weeks after birth, Muc2 knockout animals (Muc2−/−) develop spontaneous colitis and display increased susceptibility to experimental DSS colitis, presumably due to the direct contact of intestinal microbiota with the epithelia." (PMID 28707083, 2017). "The importance of this mucous layer was elegantly demonstrated using MUC2 knockout mice that developed spontaneous colitis due to increased susceptibility to enteric infections such as Citrobacter rodentium." (PMID 28323899, 2017). "Colitis would spontaneously develop in Muc2-deficient mice, indicating a critical role for MUC2 in mucosal protection." (PMID 28588585, 2017). "In DSS-induced colitis, dietary white and dark kidney beans, as well as dietary cranberry bean supplementation, enhanced the mRNA expression of MUC-2 and Tff3, and mitigated the severity of colitis and associated inflammation." (PMID 28524086, 2017). "MUC2 deficient mice were reported to have spontaneous colitis and were more susceptible to dextran sulfate sodium-induced colitis." (PMID 28379196, 2017). "Missense mutations of the MUC-2 gene in Winnie and Eeyore mice increased ER-stress-related mucin depletion, resulting in colitis." (PMID 28524086, 2017). "Muc2-deficient mice spontaneously developed colitis with diarrhea, rectal prolapse, and failure to thrive presumably by commensal bacteria in tissue." (PMID 26818460, 2015). "Muc2 deficient mice, known to develop spontaneous colitis, have been shown to robustly increase colon tumorigenesis when combined with APC mutation." (PMID 24997475, 2014). "The importance of this barrier in intestinal homeostasis is evident from studies in mice deficient in the gel-forming colonic mucin Muc2, who spontaneously develop colitis and colorectal tumors." (PMID 23977158, 2013). "Altered mucus quality caused by mutations in the Muc2 gene or defect O-glycosylation also cause colitis." (PMID 22815896, 2012). "For example, Muc2-deficient mice spontaneously develop colitis while Ig-deficient mice show hyperplasia of intestinal lymphoid follicles and the overgrowth of a segmented filamentous bacterium." (PMID 18779861, 2008). "Similarly, Muc2, the primary mucin component of the intestinal mucus layer, is essential for barrier protection, and its deficiency in mice leads to spontaneous colitis due to increased epithelial exposure to luminal microbes." (PMID 40723826, 2025). "Its ability to develop spontaneous colitis due to a point mutation in the Muc2 gene, leading to epithelial barrier dysfunction, highlights the critical role of barrier damage in triggering inflammation, making it a valuable tool for studying UC progression and potential therapy." (PMID 41196658, 2025). "In murine models, knockout of the core 3 O-glycan–synthesizing enzyme B3GNT6 leads to a marked reduction in Muc2 mucin in the colonic mucosa, increased intestinal permeability, and greater susceptibility to colitis and colorectal tumorigenesis following pathogenic challenge or chemical injury." (PMID 41301470, 2025). "By contrast, the SPF Winnie mouse model described here represents an important advance, as tumorigenesis arose in the context of a Muc2 missense point mutation — highly relevant to human disease, in which Muc2 variants and altered mucin biology have been reported in colitis." (PMID 41196658, 2025). "It was shown that activation of ERK is not only engaged in enhancing and maintaining visceral sensitivity, but is also associated with increased intestinal MUC2 expression in colitis mice by allyl isothiocyanate, and accompanied by downregulation of colonic AQP3 in an IBS model." (PMID 38634140, 2024). "Muc2-deficient mice spontaneously develop colitis and adenoma within the small and large intestine." (PMID 38979515, 2024). "Muc2-deficient mice develop severe colitis and gut inflammation." (PMID 38329121, 2024).